CGAS (cyclic GMP-AMP synthase)
Diseases named in the same sentence as CGAS in open-access papers (continued):
Sharing a sentence is not in itself a finding about the gene and the disease.
tumor (continued). "Our study uncovers an essential role for the cyclic GMP-AMP synthase (cGAS)-stimulator of interferon genes (STING) pathway, which mediates the innate immune response to cytosolic DNA, in driving large EV biogenesis and inducing a systemic immune response to tumours." (PMID 42106918, 2026). "Moreover, Mn-MOF nanoadjuvants enhanced antigen presentation efficiency by nearly two-fold through activation of the cGAS-STING pathway in dendritic cells, while Mn@RM further optimized the lymph node immune microenvironment to promote robust anti-tumor immunity." (PMID 42212971, 2026). "Simultaneously, Mn2+ potentiated the dsDNA recognition by cGAS, amplifying STING pathway activation.[65b] Following intravenous administration, the combination of NaGdF4:Nd@NaLuF4 and Mn2+ under X‐ray irradiation demonstrated robust synergistic effects in a 4T1 tumor model." (PMID 40842018, 2025). "Thus, we hypothesized that combining cholesterol-lowering drugs with radiotherapy in treating patients with CRC could potentially enhance cGAS–STING activation, resulting in increased anti-tumor activity." (PMID 40355720, 2025). "Second, our observations on immune infiltration and cGAS-STING activation may not fully capture the complexity of tumor–immune interactions." (PMID 41463247, 2025). "Beyond its role in cGAS inhibition, PCBP2 may also interact with other immunosuppressive mechanisms, such as the TGF-β/Smad pathway or ECM remodeling, further contributing to an immune-resistant tumor microenvironment." (PMID 40051782, 2025). "Moreover, cGAS-STING signaling pathway agonists can also be combined with radiotherapy, chimeric antigen receptor T Cell (CAR-T) therapy, oncolytic virus therapy to enhance tumor immunity and improve efficacy." (PMID 41333471, 2025). "In addition, cGAS-STING activation also promotes the secretion of chemokines (e.g., C-X-C motif chemokine 9 (CXCL9), CXCL10 and C-C motif chemokine ligand 5 (CCL5)), and enables CTL infiltration and tumor recognition." (PMID 40849659, 2025). "This combination therapy specifically activates the cGAS-STING signaling pathway and stabilizes the mRNA expression of the chemokine CXCL10 through an EIF4E2-dependent mechanism, thereby promoting T-cell infiltration into the tumor microenvironment and enhancing anti-tumor immune responses." (PMID 41367875, 2025). "Increased activation of the cGAS-STING pathway in cancer cells limits tumorigenesis, through the upregulation of inflammatory genes, which leads to the release of inflammatory cytokines and chemokines that slow down tumor growth and recruit anti-tumor immune cells." (PMID 40918140, 2025). "Therefore, we speculate that dsDNA released from tumor cells after CTX treatment in vivo also exists in form(s) that preferentially target APCs, which subsequently triggers the APC-intrinsic cGAS–STING pathway that leads to IFN-I production." (PMID 40227734, 2025). "Our findings reveal the critical role of cGAS-STING in mediating the secretion of CCL5, which facilitates intercellular communication between tumor cells and stromal cells during cisplatin treatment, although we do not exclude the possibility that other pathways may also contribute." (PMID 41152972, 2025). "On the other hand, excessive activation or dysregulation of the cGAS-STING pathway may trigger autoimmune responses, exacerbate chronic inflammation, and even promote tumor progression and fibrosis through mechanisms such as immune tolerance and T cell exhaustion." (PMID 41438738, 2025). "The phosphorylation activation of the cGAS-STING pathway initiates a complex type I interferon-driven inflammatory response, enhancing the activation of DCs and facilitating the cross-presentation of tumor antigens, thereby supporting the subsequent initial activation of T cells." (PMID 40761260, 2025).
tumor (continued). "Additionally, succinate produced by Fusobacterium nucleatum may inhibit the cyclic GMP-AMP synthase (cGAS) and interferon (IFN) signaling pathway, resulting in decreased levels of the chemokines CCL5 and CXCL10 within the tumor microenvironment." (PMID 40297806, 2025). "This paradoxical RP–survival association may reflect radiation-induced immune activation, as radiotherapy remodels the TME via cGAS–STING/I-type interferon signaling, enhancing tumor neoantigen presentation, dendritic cell maturation, and CD8+ T-cell infiltration." (PMID 41302177, 2025). "C-di-AMP synergizes with radiotherapy-induced tumor antigen release, particularly double-stranded DNA, to enhance dendritic cell maturation and antigen presentation, promoting IFN production and activating CD8+ cytotoxic T cells in a cGAS- and STING-dependent manner." (PMID 40699664, 2025). "Finally, we observed that, compared to free CPT, the nanoparticles upregulated cGAS expression, suggesting that the nanoparticles may activate the cGAS/STING signaling pathway in tumor cells, inhibiting tumor cell invasion." (PMID 41050083, 2025). "These engineered CAR-Ms selectively engulfed NKG2DL-positive tumor cells through FcγRI-mediated phagocytosis while simultaneously secreting pro-inflammatory cytokines (e.g., TNF-α, IL-12), a dual functional output driven by coordinated activation of the PI3K-AKT and cGAS-STING signaling pathways." (PMID 41388305, 2025). "However, a recent study demonstrated that activation of the cGAS-STING pathway, not the tumor mutational burden (TMB), is the critical determinant of T-cell priming and ICB efficacy in MSI-H tumors." (PMID 40817248, 2025). "Thus, enhanced AR activity in males may suppress cGAS–STING‐mediated innate immunity, promoting tumour immune evasion and therapy resistance." (PMID 41275427, 2025). "Importantly, cGAS inhibitor treatment markedly ameliorated liver metastasis, performed splenectomy did not further alleviate liver metastatic tumor burden in these mice." (PMID 39737867, 2025). "Notably, preclinical research has emphasized the immunomodulatory capabilities of PARPi in activating the cytoplasmic DNA recognition cGAS-STING pathway, leading to elevated PD-L1 expression, a type-1 interferon (IFN-I) response, and tumor infiltration by lymphocytes 46-49." (PMID 40959288, 2025). "The synergistic enhancement of the cGAS–STING pathway triggered by this engineered nano-agonist activates the immune effect, which promotes the infiltration of CT8+ and the maturation of DC and establishes long-term anti-tumor immune memory while eliminating the primary tumor." (PMID 40486836, 2025). "Thus, it is not surprising that tumor cells induce TREX1 upon CIN in a cGAS/STING-dependent manner as an adaptive feedback mechanism to promote removal of cytosolic DNA, and thus, allow for immune evasion." (PMID 40098954, 2025). "Cyclic dinucleotide agonists, such as 2′5′-cGAMP, can enhance the activation level of STING proteins and activate the cGAS/STING signaling pathway in neighboring cells via transport vesicles as well as intercellular junctions, thereby improving immune recognition of viral particles or tumor cells." (PMID 39601590, 2025). "This aberrant dsDNA activates the cGAS-STING pathway in cancer cells and promotes production of IFNβ and pro-inflammatory chemokines, which contribute to the recruitment of dendritic cells and immune effector cells into tumor, thereby eliciting an anti-tumor immune response." (PMID 39990655, 2025). "Among these is the cGAS-STING-PERK-eIF2 axis that affects cellular aging, organ fibrosis, and the regulation of the autophagy by STING, as well as the activation of the NFκB by STING, all resulting in inflammatory conditions, autoimmune disorders, and tumour immunity." (PMID 40552157, 2025).
tumor (continued). "Tumor-intrinsic mechanisms include a low burden or poor quality of neoantigens, defects in antigen presentation, and aberrant regulation of immune-evasive signaling pathways such as cyclic guanylate (GMP)-adenosine monophosphate (AMP) synthase-stimulator of interferon genes (cGAS-STING) pathway." (PMID 40849659, 2025). "However, due to the immunosuppressive TME and problems such as tumor immune escape by immune checkpoint blockade (ICB) and adoptive cell transfer (ACT), the activation of the cGAS–STING pathway by RT remains transient and suboptimal, and it is unable to maintain strong antitumor immunity." (PMID 41287826, 2025). "Originally, the cGAS–STING pathway was identified as a mechanism that protects the host from viral infection by activating IFN signaling, but in cancer, activation of this process by CIN may lead to tumor cell death." (PMID 40136696, 2025). "Since Evofos treatment is associated with DNA damage under hypoxia, we anticipated that this may further contribute to the cGAS-STING pathway and elicit type I IFN signaling cascades, enhancing the anti-tumor activity of NK cells and thereby improving treatment outcomes in breast cancer." (PMID 40563638, 2025). "Deficiency for STING or cGAS and STING had no impact on the tumor-free survival of mice lacking the tumor suppressors p53603 or RnaseH2,604 respectively, suggesting that in these tumor prone models cGAS-STING signaling is redundant for the control of spontaneous endogenous tumorigenesis in mice." (PMID 40102400, 2025). "Micronuclei are known potent activators of the cGAS/STING pathway, which drives type 1 interferon production, providing a rationale for leveraging existing DNA checkpoint inhibitors as a novel means of eliciting an immunological anti-tumour response in combination with low-dose radiotherapy." (PMID 39403376, 2024). "Thus, the intact cGAS-STING signaling pathway serves as a pivotal determinant not only for tumor cells but also for regulating the antitumor immune response in immune cells." (PMID 38512518, 2024). "Moreover, VC therapy had no substantial effect on tumor vessel coverage by pericytes, intratumoral hypoxia, and CD8+ T cell infiltration after tumor cGAS deficiency and host STING inhibition." (PMID 38177099, 2024). "Disparity B reflects the difference in ISRE reporter activity of THP1‐Lucia ISG cells treated with a combination of exosomes and 2′3′‐cGAMP with or without STF‐1623, which indicates the inhibitory effect of tumor exosomal ENPP1 on the cGAS‐STING pathway through hydrolysis of 2′3′‐cGAMP." (PMID 38498770, 2024). "Tumor transcriptomic analysis from SB02024-treated mice revealed increased expression of gene markers for T cells, Natural killer (NK) cells, macrophages, and neutrophils, which correlated with a notable upregulation of IFN signaling pathways, especially the cGAS-STING pathway." (PMID 40395527, 2024). "Similarly, PCM nano-inducers enhance proteotoxic stress through cuproptosis, leading to the release of mitochondrial DNA that activates the cGAS-STING pathway, thereby initiating a robust immune response that significantly inhibits tumor progression and metastasis." (PMID 39867656, 2024). "Since PRMT3 inhibition activated cGAS/STING signaling through promoting mtDNA release, we decided to examine whether cGAS/STING hyperactivation directly contributes to the delayed tumor progression and increased T cell infiltration observed in Prmt3-KO or PRMT3 inhibitor-treated tumors." (PMID 39256398, 2024). "Beyond its anti-tumor properties, eribulin has been observed to enhance the cytotoxic response of CD8-positive lymphocytes and activate cyclic GMP-AMP synthase-stimulator of interferon genes (cGAS-STING)-mediated immune responses, thereby boosting overall cytotoxic immune activity." (PMID 38975372, 2024).
tumor (continued). "Thus, the formation of positive feedback loop between inactivated cGAS‐STING signaling and hyperactivated AKT1 is a crucial determinant of endocrine resistance by mediating immunosuppressive microenvironment and promoting tumor proliferation." (PMID 39023171, 2024). "Furthermore, some tumors may exploit mechanisms to inhibit the cGAS-STING pathway, thereby evading immune detection and promoting tumor progression." (PMID 40018367, 2024). "However, to our knowledge, reactivation of silenced cGAS expression and inhibition of NF-κB p65 overexpression have not been carried out simultaneously in tumor therapy." (PMID 38782895, 2024). "However, the selective pressure for tumor cells could decrease both cGAS and STING expression in human cancers protecting tumor cells." (PMID 39020402, 2024). "In cGAS- and STING-deficient mice, Mn treatment did not lead to an increase in CD8+ or CD4+ T cells, thus demonstrating Mn’s reliance on the cGAS pathway to alter the tumor microenvironment." (PMID 39050748, 2024). "Indeed, the cGAS–STING pathway seems to have a dual role in cancer immunity, both promoting cell growth through modulation of the tumor microenvironment and otherwise activating anti-tumoral inflammatory response, particularly via induction of tumor-specific CD8+ T cells." (PMID 38254772, 2024). "Manganese activates cGAS-STING to promote mitochondrial lipid peroxidation and ROS production by releasing type I IFN to reduce DHODH function, thereby inducing ferroptosis in tumour, providing a new strategy to complement existing anti-tumour treatment options." (PMID 39183465, 2024). "The cGAS-STING pathway utilises its own DNA sensing function to perceive enriched genomic DNA in CD8+ T cells, initiating the activation of the cGAS-STING innate immune signalling pathway to prevent excessive activation of CD8+ T cells, enhancing their stemness and anti-tumour function." (PMID 39322862, 2024). "Therefore, we hypothesized that zebularine relies on cGAS-STING signaling to facilitate antigen processing and presentation, thereby enhancing cancer cell clearance by tumor-specific cytotoxic T cells." (PMID 38755254, 2024). "For example, inhibition of CCF activation downstream of cGAS-STING signaling in chronic inflammation may be beneficial during aging, but it may also impair micronuclei-initiated cell-intrinsic immune detection and tumor suppressor signaling." (PMID 39114669, 2024). "Beyond its role in pathogen defense, the cGAS-STING pathway exhibits pleiotropic effects, including the regulation of cellular stress responses, clearance of damaged cells, and maintenance of immune homeostasis, thereby establishing a robust defense against viral and tumor challenges 58-60." (PMID 39439455, 2024). "Thus, for this innate sensing mechanism to function cGas-generated cGAMP must be transmitted from irradiated cancer cells to STING-expressing non-cancer cells of the tumor stroma." (PMID 39622844, 2024). "Thus, we tested the effect of the pharmacological DDR inhibitor (DDRi) in PBMCs and in three-dimensional spheroid co-culture of PBMCs and LC cell lines; we found that DDRi strongly increased cGAS-STING expression and tumor infiltration ability of immune cells in NR and R patients." (PMID 38672164, 2024). "Thus, the cGAS-STING pathway plays a dual role—temporary stimulation of this pathway has beneficial effects in managing tumours and viruses, whereas continuous stimulation contributes to inflammation-induced tumour formation." (PMID 39183465, 2024). "Additionally, tumor-infiltrating effector memory and central memory CD8+ T cells, but not naïve CD8+ T cells (which play a bystander role in tumor killing), correlated with cGAS levels." (PMID 39449023, 2024). "Furthermore, high tumor LRRC8C expression was associated with low hypoxia marker GLUT1 expression in the high cGAS expression group, but not when cGAS was low expressed in HCC tissues." (PMID 38177099, 2024).
tumor (continued). "The cGAS-STING pathway is a vital innate immune signaling pathway that detects cytosolic DNA and activates downstream signaling cascades, resulting in the production of type I interferons and other inflammatory cytokines, which initiate anti-tumor immune responses 10-12." (PMID 39439455, 2024). "Activating cGAS-STING signaling with small molecule drugs can trigger relevant innate immune signals, activating various immune cells, including dendritic cells, macrophages, NK cells, and CD4+ and CD8+ T cells, resulting in significant tumor shrinkage or even complete regression in vivo." (PMID 39763653, 2024). "In addition, RNA-seq data from a research group led by Charles Spruck indicated activation of antiviral pathways within tumor cells, including RIG-I/MDA5-MAVS, cGAS-STING, interferon IFN pathways, surface antigen presentation pathways, and various cytokines recruiting T cells and NK cells." (PMID 38817870, 2024). "Indeed, tumor exosomal ENPP1 may have a strong degradation activity for any form of 2′3′‐cGAMP, thus inhibiting cGAS‐STING signaling." (PMID 38498770, 2024). "The engineered EVs enhance the intracellular delivery of cGAS via an endosomal escape mechanism, preferentially activating STING in myeloid cell populations within the TME to trigger a multifaceted shift to a “hot” T-cell-inflamed TME that inhibits tumor growth." (PMID 38518087, 2024). "Furthermore, a multi‐stimuli activatable peptide nanodrug is designed for site‐specific delivery of different peptides, simultaneously activating the cGAS‐STING pathway and blocking PD‐1/PD‐L1 pathway, ultimately initiating robust and durable T cell anti‐tumor immunity." (PMID 38233164, 2024). "Notably, compared to EBRT, RNT could generate more persistent and powerful cGAS-STING activation, and then triggered much stronger systemic anti-tumor immunity." (PMID 38831378, 2024). "Activation of the cGAS/STING pathway and production of immunomodulatory molecules such as INF-α, IL-6, CXCL9 and CXCL10 were described to be involved in the enhanced migration of immune cells in cancer, particularly macrophages, and regulate anti-tumor immune response." (PMID 38587186, 2024). "Given that 5-FU/oxaliplatin activates cGAS/STING signaling and elevates PD-L1 expression, we hypothesized that the combination of 5-FU/oxaliplatin and anti-PD-1 treatment would effectively inhibit tumor growth in immune competent mice." (PMID 39469633, 2024). "To examine whether these released tumor-derived DNA fragments could be internalized by surrounding immune cells to activate their cGAS-STING pathway and induce type I interferon secretion, we conducted coculture experiments using aAGd-NWs+RT-treated CT26 tumor cells and RAW264.7 cells." (PMID 38724527, 2024). "Thus, the cGAS-STING signaling pathway functions as the core player of the cellular immune system, and its activation represents a promising direction for the development of anti-tumor medicines." (PMID 38238314, 2024). "Furthermore, chemotherapy may boost the immune response by inducing apoptosis in tumor cells and increasing the expression of MHC class I molecules of the cGAS-STING pathway, which is essential in this process." (PMID 38549044, 2024). "Furthermore, cGAS-STING agonists stimulate the secretion of the chemokine CXCL10 in an IFN-I-dependent manner, which facilitates the recruitment of antigen-specific CD8+ T cells to infiltrate into the tumor and elicit an effective antitumor immune response." (PMID 38999073, 2024). "PtII complexes, Pt1and Pt2, acted as photoactivators of the cGAS-STING pathway, disrupted the mitochondrion and nuclear envelope under light exposure, resulting in cytoplasmic leakage of mtDNA and activation of the cGAS-STING pathway to induce pyroptosis in tumor cells." (PMID 38195584, 2024).